RN7SKP238 (RN7SK pseudogene 238)
Gene: Miscellaneous RNA gene on chromosome 10 (85,650,012 to 85,650,260, reverse strand). Ensembl gene ENSG00000252292.
Homologues: Orthologues: chimpanzee 7SK (97% identical), guinea pig 7SK (50% identical), mouse Gm54581 (50% identical). Paralogues in human: RN7SKP8 (61% identical), RN7SKP255 (61% identical), RN7SKP37 (60% identical), RN7SKP93 (60% identical), 7SK (59% identical), RN7SKP124 (59% identical), RN7SKP151 (59% identical), RN7SKP273 (59% identical), RN7SKP133 (59% identical), RN7SKP176 (59% identical), RN7SKP211 (59% identical), RN7SKP243 (59% identical), and 284 more.